INS (insulin)
Diseases named in the same sentence as INS in open-access papers (continued):
Sharing a sentence is not in itself a finding about the gene and the disease.
chronic kidney disease (continued). "Its role in patients not on insulin treatment is limited.Inaccurate in Chronic Kidney Disease (CKD).UCPCR affected by gender and muscle mass as a result of differences in creatinine concentration.UCP alone is less sensitive than when expressed as ratio to creatinine." (PMID 41355468, 2026). "Furthermore, those with higher HbA1c levels, presence of comorbidities such as chronic kidney disease (CKD), chronic pulmonary disease, cerebrovascular disease, cardiovascular disease (CVD), hypertension, and insulin-treated ones are more likely to get hospitalized." (PMID 36118201, 2022). "Furthermore, the adjustment for chronic kidney disease and insulin use did not affect the mortality." (PMID 31111663, 2020). "A longer prospective study evaluating insulin sensitivity by the reference method, both at baseline and at follow-up, over a range of eGFR values is needed to understand the physiopathology of change in insulin sensitivity in people with and without chronic kidney disease." (PMID 29855339, 2018). "Furthermore, in patients with nondiabetic chronic kidney disease stages 2 and 3, a low fructose diet exerted a decrease in uric acid, arterial blood pressure, and insulin concentration." (PMID 30416829, 2018). "Third, the limited data in the literature did not allow us to separate patients receiving different insulin regimens, into groups based on whether they had acute kidney injury, chronic kidney disease or end-stage renal disease on hemodialysis." (PMID 27148740, 2016). "Many studies have investigated the relation between chronic kidney disease (CKD) and insulin sensitivity, but it is still not clear whether reduced insulin sensitivity precedes CKD or the inverse." (PMID 29855339, 2018). "ADA/EASD recommends adding sulfonylurea (oral antidiabetic) to insulin as first-line combination therapy for low-income type 2 DM patients without a history of ASCVD and chronic kidney disease (CKD)." (PMID 38243951, 2024).
myocardial infarction (316 papers, 2001 to 2026). Gross necrosis of the myocardium, as a result of interruption of the blood supply to the area, as in coronary thrombosis. "The adjusted risk for myocardial infarction was significantly higher in diabetic patients on insulin therapy than diabetic patients on oral antidiabetic drugs (adjusted HR = 3.03 [1.09–8.43], p = 0.034)." (PMID 41464751, 2025). "A study lasting from 12 to 26 weeks has shown that a low GI diet gradually enhances blood sugar control and insulin sensitivity, reducing the risk of heart attacks." (PMID 38609963, 2024). "In this retrospective cohort study, we observed an increased risk of all-cause mortality and decreased risk for myocardial infarction for individuals using an LA plus SA insulin regimen compared with those using an LA insulin regimen alone." (PMID 34559229, 2021). "Other studies confirmed these results by proving that patients undergoing coronarography while on metformin treatment had a 69% lower risk of acute myocardial infarction than those on insulin therapy." (PMID 32429441, 2020). "One study has compared the effect of metformin vs. sulfonylureas or insulin treatments on a 10-year period; the first group reported a 33% decrease in acute myocardial infarction risk while the latter a 15% decrease." (PMID 32429441, 2020). "Metformin intake can remarkably weaken neointimal hyperplasia in fructose-caused insulin- resistant rats and myocardial reshaping and neutrophil recruitment after myocardial infarction in rats." (PMID 33117278, 2020). "mAb A-mediated cardioprotection post-myocardial infarction is associated with improved insulin sensitivity and a selective enhancement of glucose oxidation via, at least in part, enhancing branched chain amino acids catabolism." (PMID 30626440, 2019). "In this study, we demonstrated that myocardial infarction causes IR, as well as impaired vasodilation in response to ACh and insulin in aortas, decreased activities of PI3K, Akt, and eNOS, and attenuated insulin-induced PI3K/Akt/eNOS phosphorylation." (PMID 25907785, 2015). "Heart failure and myocardial infarction are insulin-resistant states that are associated with a significant risk for either concurrently having or subsequently developing newly-onset diabetes." (PMID 23777457, 2013). "In addition, variants in this gene are associated with various phenotypes including BMI, insulin, bipolar disorder and myocardial infarction." (PMID 38383672, 2024). "Additionally, the study also found a reduced risk of myocardial infarction and death from any cause in patients receiving sulfonylurea–insulin therapy." (PMID 33598483, 2021). "In this cohort study of 57 278 adults, addition of short-acting insulin was associated with increased all-cause mortality compared with long-acting insulin alone and a decreased risk of acute myocardial infarction, with limited evidence of a difference in congestive heart failure." (PMID 34559229, 2021). "Moreover, oral medication was a risk indicator for later myocardial infarction when compared to diet only and insulin therapy." (PMID 31774849, 2019). "Although successful blood pressure treatment can reduce stroke risk by up to 40%, concomitant reductions in myocardial infarction are less pronounced (15-25%), suggesting a role of insulin resistance and other metabolic defects in susceptibility to myocardial infarction." (PMID 28130354, 2017). "Furthermore, a gain-of-function variant in TRB3 gene that has been identified and extensively characterized (i.e. Q84R, where arginine replaces glutamine at position 84; rs2295490) has been associated with in vitro and in vivo vascular insulin resistance and earlier onset of myocardial infarction." (PMID 34051802, 2021). "Interestingly, there is a study suggesting that insulin glargine might be associated with a lower risk of acute myocardial infarction, compared to the other long-/intermediate-acting insulin use." (PMID 34436438, 2021).
myocardial infarction (continued). "To improve the reliability of our GIP to CAD/myocardial infarction MR analysis, we considered the possible confounding phenotypes and tested for their association with our instrumental variable rs1800437, which is associated with insulin secretion, BMI and other related phenotypes." (PMID 31974732, 2020). "Thus, the risk of mortality through myocardial infarction was 15% lower in patients with sulphonyl urea or insulin treatment compared to those who were only recommended lifestyle changes and 39% lower in patients treated with metformin than those to whom only lifestyle changes were recommended." (PMID 32429441, 2020). "The 10-year incidence of myocardial infarction was significantly higher in diabetic patients on insulin therapy compared with diabetic patients on oral antidiabetic drugs." (PMID 41464751, 2025). "The 10-year incidence of myocardial infarction was higher in diabetic patients on insulin therapy (10.0%) versus diabetic patients on oral antidiabetic drugs (3.0%)." (PMID 41464751, 2025). "The trial demonstrated that intensive insulin treatment significantly reduced mortality rates and recurrent myocardial infarctions in the immediate post-MI phase." (PMID 39913488, 2025). "In the present study, In vivo experiments demonstrated that ISL attenuated myocardial infarct size, decreased serum markers of myocardial injury, improved left ventricular systolic function, and enhanced insulin sensitivity." (PMID 40365313, 2025). "Of note, cardiovascular comorbidities were pronounced in prevalent insulin users: 9.4% of T1D prevalent users were diagnosed with myocardial infarction, ischemic stroke, or unstable angina pectoris by the EOS." (PMID 38273701, 2024). "GCGR mAb enhanced insulin signaling and branched chain amino acid catabolism but inhibited the signaling pathway target of rapamycin to improve cardiac function after myocardial infarction." (PMID 37596940, 2023). "In the present study, we demonstrate that lack of the insulin signaling protein TBC1D4 in mice abrogates cardiac glucose uptake in response to insulin and aggravates cardiac damage after myocardial infarction." (PMID 36707786, 2023). "We recorded eight deaths during the four-month active follow-up period because of intracranial hemorrhage, insulin poisoning, car accident (one each), and five heart attacks." (PMID 37464440, 2023). "This included incidence of myocardial infarction, cerebrovascular accident, anastomotic leaks, urinary tract infections, systemic infections, pancreatitis, graft rejection at 3 months and resumed insulin use (at 1 year and also 5 years)." (PMID 38370534, 2023). "Insulin and IGF1 can be cardioprotective: insulin/IGF1 reduce infarct size in ex vivo models of myocardial infarction, and cardiomyocyte-specific expression of IGF1 in mice protects against myocardial infarction in vivo." (PMID 35766350, 2022). "Without a doubt, HF can be an outcome of atherosclerotic CVD, but this phenotype is formed much later and is associated with a complicated course of ischemic heart disease (myocardial infarction (MI)), a longer duration of DM, and insulin therapy." (PMID 35216477, 2022). "CII is the preferred route and delivery method of insulin in critically ill patients with hyperglycemic crises, such as perioperative care of cardiac surgery, cardiogenic shock, myocardial infarction, and acute ischemic stroke." (PMID 36584121, 2022). "This ketogenic state can be triggered by various stressors including infection, surgery, myocardial infarctions, omission of insulin dosage, as well as low carbohydrate diet." (PMID 34123681, 2021). "The clinical evidence of insulin administration on outcomes in myocardial infarction remains mixed and inconclusive." (PMID 33463901, 2021). "Insulin can also improve cardiac function, and in patients post myocardial infarction and in sepsis, the combination of glucose and insulin infusion improves cardiac function." (PMID 34368024, 2021).
myocardial infarction (continued). "Other studies on statin conducted for a relatively short period also demonstrated elevated blood glucose levels, and statin treatment for only a few days in the early phase of acute myocardial infarction also reduced insulin sensitivity." (PMID 33481866, 2021). "On the other hand, the “Keyword” topics included the following clusters: apoptosis, insulin resistance, mitophagy, asthma, inflammation, neuroprotection, myocardial infarction, resveratrol, exercise, and mesenchymal stem cell." (PMID 34095256, 2021). "Patients treated with insulin have worse outcomes compared to patients treated with oral hypoglycemics or diet in the setting of acute myocardial infarction, after PCI and after CABG." (PMID 33113760, 2020). "Previously, negative associations of lysoPC a C17:0 levels with high-sensitivity C-reactive protein (hsCRP), interleukin-6, insulin, and myocardial infarction have been found." (PMID 31406173, 2019). "Insulin has been suggested to inhibit cardiomyocytes apoptosis, protects H9c2 cells against doxorubicin toxicity, and decrease the size of myocardial infarction in whole heart ischaemia-reperfusion model." (PMID 30211323, 2018). "TNFα levels are increased after acute myocardial infarction and induce acute inflammatory responses, including vascular insulin resistance." (PMID 29464018, 2018). "She expired with hypotensive shock from a new myocardial infarction soon after completion of treatment with insulin infusion." (PMID 29974021, 2018). "DIGAMI 1 and DIGAMI 2 evaluated insulin therapy (using glucose-insulin-potassium infusions) after a myocardial infarction and the studies came to opposite conclusions (DIGAMI 1: benefit; DIGAMI 2: no benefit)." (PMID 27188479, 2016). "Insulin has been shown to improve cardiac function in the setting of acute myocardial infarction, ischemia and reperfusion injury, sepsis and hemorrhagic shock." (PMID 27651131, 2016). "NDRG2 is phosphorylated in response to insulin stimulation and has been identified as a mediator of the cardioprotective effects of insulin on ischemia-reperfusion injuries following myocardial infarctions." (PMID 27657503, 2016). "The DIGAMI study has demonstrated that diabetic patients with acute myocardial infarction on intensive insulin treatment have a better prognosis and an absolute reduction in mortality." (PMID 26089882, 2015). "In myocardial infarction rats, levels of fasting blood glucose and serum insulin were significantly higher compared with those in Sham rats (P < 0.05, P < 0.01, respectively)." (PMID 25907785, 2015). "In a study of acute myocardial infarction patients, it was reported that insulin infusion attenuated the rise of CRP and enhanced fibrinolysis." (PMID 24563867, 2014). "Adiponectin, a 244-amino acid protein secreted by adipocytes has insulin-sensitizing, anti-inflammatory, and endothelial protective effects and exerts a protective role in myocardial infarction (MI) and coronary heart disease (CHD)." (PMID 25200659, 2014). "Normalization of blood glucose with insulin 5 min before the preconditioning procedure served to partially restore the protective effect of preconditioning against myocardial infarction (33.0 ± 3.7%, P < 0.05 versus control or HG mice)." (PMID 24371503, 2013). "A meta-analysis of 35 trials including 8,478 patients examined the effect of insulin on mortality in the hyperglycemic critically ill patient, mostly after myocardial infarction." (PMID 23574917, 2013). "Second, ABG is a common acute adrenergic signal of stress and is present in myocardial infarction, as well as other severe acute illnesses, whereas increased catecholamine levels result in decreased insulin secretion and increased insulin resistance." (PMID 22553938, 2012). "In patients with acute myocardial infarction, insulin also suppressed C-reactive protein (CRP) and serum amyloid A (SAA) by 40% within 24 h of the start of the insulin infusion while glucose concentrations rendered unchanged." (PMID 23497719, 2012).
myocardial infarction (continued). "In this study, acute intensive glucose lowering therapy with insulin-glucose infusion led to a reduction in mortality after 3.4 years followup in DM patients with acute myocardial infarction." (PMID 22347666, 2012). "Malmberg randomly allocated patients with diabetes mellitus and acute myocardial infarction to intensive insulin therapy (n = 306) or standard treatment (controls, n = 314)." (PMID 20137090, 2010). "HOMA correlated positively with male gender, body mass index, former myocardial infarction, eGFR, glucose and insulin as well as the use of beta blockers, statins and antiplatelets." (PMID 21156037, 2010). "In patients with acute myocardial infarction, low-dose insulin has anti-inflammatory, antioxidant and pro-fibrinolytic effects, independently of a decrease in blood glucose levels." (PMID 19055829, 2008). "Favorable clinical outcomes have been observed with glucose-insulin-potassium infusion (GIK) in acute myocardial infarction (MI)." (PMID 15932638, 2005). "It is well acknowledged that H2S has been involved in multitudinous physiological response processes, such as anti‐inflammation, oxidative stress, vasoregulation, neuromodulation, post‐myocardial infarction reperfusion damage protection, and insulin resistance." (PMID 37492969, 2023). "There are certain stress mediators which are released during myocardial infarction that cause high blood glucose levels independent of insulin secretion." (PMID 35734745, 2022). "The Southern European Atlantic diet (SEAD), a common diet in the Iberian Peninsula, enabled reduced concentrations of C-reactive protein (CRP), triglycerides, and insulin, which could help prevent myocardial infarction." (PMID 35276919, 2022). "In addition, there is evidence to show that an initial activation of insulin/Akt pathway, one day after myocardial infarction (MI) injury in rats, was attenuated at one week after MI injury." (PMID 32839388, 2020). "She had required insulin and died at the age of 49 years from myocardial infarction." (PMID 30968599, 2019). "Our results are in contrast to several studies in ICU patients that suggested that insulin infusion has protective effects on apoptosis after myocardial infarction and induced lowering of inflammation markers, but those studies were not designed to assess clinical outcomes." (PMID 30742240, 2019). "Local IGF-1 signaling in heart has anti-apoptotic and regenerative effects and is associated with improvements in cell growth, contractility, cardiac output, stroke volume, ejection fraction, functional recovery following myocardial infarction and insulin sensitivity." (PMID 29708498, 2018). "Interestingly, findings from the recent 20-year follow-up of the DIGAMI 1 cohort supported that insulin-based intensified glycemic control after acute myocardial infarction increased survival, with a lasting effect of at least 8 years." (PMID 30402502, 2018). "However, to compensate the lower level of insulin in blood, administration of insulin injection followed by intensive treatment with multidose subcutaneous insulin can reduce up to 30% of mortality in diabetic patients with acute myocardial infarction." (PMID 27034931, 2016). "A more recent study reported that Pioglitazone (an insulin sensitizing drug with cardio protective effect, it attenuates cardiac fibrosis) increased miR-711 levels in myocardial infarction rats and miR-711 directly targeted and downregulated SP1, leading to reduced collagen-I levels." (PMID 24278182, 2013). "Hyperinsulinemic-euglycemic clamps coupled with 2-[14C]deoxyglucose were employed 36 days post-myocardial infarction (13 weeks of high-fat feeding) to assess systemic insulin sensitivity and insulin-mediated, tissue-specific glucose uptake in the conscious, unrestrained mouse." (PMID 24007410, 2013). "However, insulin supplementation significantly decreased MI/R-induced apoptotic death and myocardial infarction." (PMID 23922853, 2013).